LGALS3 (galectin 3)
Diseases named in the same sentence as LGALS3 in open-access papers (continued):
Sharing a sentence is not in itself a finding about the gene and the disease.
cervical carcinoma (continued). "Additional examination revealed that bergenin is a powerful anti-angiogenic substance, as it decreased the levels of essential angiogenic proteins, such as Galectin 3 and MMP-9, in cervical cancer cells at the cellular level, as demonstrated by a western blotting assay." (PMID 39834829, 2024). "This is the first report showing that bergenin firstly reduced MMP-9 levels and secondly bergenin binds MMP-9 more efficiently as compared to galectin-3, suggesting a cumulative effect of bergenin on Galectin 3 and MMP 9 leads to reduced migratory characteristics in cervical carcinoma cells." (PMID 38961106, 2024). "Cumulatively, our data provide novel insight into the anti-angiogenic mechanism of bergenin in cervical carcinoma cells by modulation of multiple angiogenic proteins like Galectin-3 and MMP-9 which warrant its further development as an anticancer agent in cervical cancer." (PMID 38961106, 2024). "First, we found that a negative correlation of uPAR with both galectin-3 and p16 in cervical cancer patients." (PMID 32488496, 2020). "In this study, we observed that EP2 in combination with negative EP3 or high galectin-3 was a prognostic factor for survival in cervical cancer patients." (PMID 31980713, 2020). "Our study previously demonstrated that galectin-3 expression is correlated with a poor prognosis in the overall survival analysis of cervical cancer patients with no or low p16 expression." (PMID 31980713, 2020). "We demonstrated that the EP2 receptor is a prognostic factor for the overall survival in the subgroup of negative EP3 and high galectin-3 expressed cervical cancer patients." (PMID 31980713, 2020). "In the present study, we could observe that the EP2 receptor in combination with high galectin-3 or negative EP3 was a significant prognostic factor for survival in cervical cancer patients." (PMID 31980713, 2020). "The immunohistochemical method was applied to detect ezrin and galectin-3 expressions in normal cervix tissues (n=30), cervicitis tissues (n=28), cervical intraepithelial neoplasia (CIN) tissues (classified as I-III, n=89), and cervical carcinoma tissues (n=84)." (PMID 28355349, 2017).
depression (15 papers, 2019 to 2025). "Galectin‐3 (Gal‐3) mediates inflammation and host defense through cytokines, which are also associated with severe depression." (PMID 41404534, 2025). "In this study, two proteins (CSPG3 and GCKR) were linked with eight NAFLD risk factors (BMI, waist circumference, smoking initiation, major depression, iron levels, C-reactive protein levels, galectin-3, and HDL cholesterol)." (PMID 38782984, 2024). "Galectin-3 has been linked to depression, heart failure, coronary artery disease, and all-cause mortality." (PMID 34045984, 2021). "Lower levels of sTWEAK and HDL-cholesterol, higher levels of galectin-3, the use of antidepressants, and age were independently associated with depression." (PMID 33261587, 2020). "As immuno-inflammatory changes and the activation of the hypothalamic pituitary axis are part of the stress response, which is involved in depression, it would also be interesting to explore associations between sTWEAK, galectin-3 and cortisol secretion." (PMID 33261587, 2020). "Galectin-3 levels were measured by means of a sandwich enzyme-linked immunosorbent assay, and anxiety was assessed using the Hospital Anxiety and Depression Scale (HADS)." (PMID 33024450, 2020). "Lower levels of sTWEAK and HDL-cholesterol and higher levels of galectin-3 were independently associated with depression in T1DM." (PMID 33261587, 2020). "Low levels of sTWEAK and HDL-cholesterol and high levels of galectin-3 were independently associated with depression in T1DM." (PMID 33261587, 2020). "Systematic exploration of these T1DM patients showed that self-reported depression was associated with inadequate glycemic control, midnight salivary cortisol secretion, galectin-3, and inversely with HDL-cholesterol." (PMID 33261587, 2020). "We have previously found that depression in T1D patients was associated with high galectin-3 serum levels, inadequate glycemic control, high midnight salivary cortisol secretion, and low HDL-cholesterol levels in T1D patients." (PMID 31752995, 2019). "To our knowledge, we are the first to explore the associations between Gal3BP and sex, galectin-3, sCD163, depression, metabolic factors, and life style variables in patients with T1D." (PMID 31752995, 2019). "Our study suggested that GCKR may affect NAFLD through modifiable risk factors, such as waist circumference, smoking, depression, C-reactive protein levels, galectin-3, and HDL cholesterol." (PMID 38782984, 2024). "We hypothesised that female sex, galectin-3, sCD163, and depression, previously linked to CVD and mortality, were associated with Gal3BP in a setting of patients with T1D." (PMID 31752995, 2019). "The aim was to explore whether female sex, sCD163, galectin-3, and depression were associated with Gal3BP in patients with type 1 diabetes." (PMID 31752995, 2019). "In this cohort of patients with T1D we have previously found that depression was associated with anxiety, inadequate glycaemic control, high midnight cortisol secretion, and with galectin-3, an inflammatory biomarker which both predicts heart failure and contributes to cardiac dysfunction." (PMID 30885233, 2019). "The main aim was to explore whether the immuno-inflammatory variables Gal3BP, sCD163, and galectin-3 were independently associated with alexithymia controlling for depression, anxiety, metabolic and life style factors, medication, and cardiovascular complications." (PMID 34045984, 2021). "We explored and adjusted for relevant variables previously linked to CVD: MMP-2, MMP-9, MMP-14, TIMPS, galectin-3, CRP, metabolic variables, life style variables, depression, and thyroid disease." (PMID 34702365, 2021). "Several DAMPs have been implicated in depression, including high mobility group box-1 (HMGB-1), extracellular ATP, purine bases and metabolites, heat shock proteins (HSPs), S100 proteins, and galectin- 3 (Gal-3)." (PMID 37252156, 2023).
depression (continued). "With this new finding of lower HDL-cholesterol levels linked to depression in T1D patients, we have altogether demonstrated four biological links to depression, increased midnight cortisol secretion, impaired glycemic control, increased galectin-3 levels, and decreased HDL-cholesterol levels." (PMID 30885233, 2019). "Age (per year) (AOR 1.05, p = 0.027), low sTWEAK (< 7.2 ng/ml) (AOR 9.0, p = 0.006), high galectin-3 (AOR 6.3, p = 0.001), HDL-cholesterol (per mmol/l) (inversely) (AOR 0.1, p = 0.006), and use of antidepressants (AOR 8.4, p < 0.001), were associated with depression." (PMID 33261587, 2020). "Low sTWEAK (adjusted odds ratio (AOR) 9.0, p = 0.006), high galectin-3 (AOR 6.3, p = 0.001), HDL-cholesterol (per mmol/l) (AOR 0.1, p = 0.006), use of antidepressants (AOR 8.4, p < 0.001), and age (per year) (AOR 1.05, p = 0.027) were associated with depression." (PMID 33261587, 2020). "High Gal3BP was neither associated with galectin-3 nor depression." (PMID 31752995, 2019). "Remarkably, previous studies showed the role of Galectin-3, TGF-β, and PAI-1 in the pathophysiology of depression." (PMID 34516574, 2021). "In particular, the role of adipokines Galectin-3, transforming growth factor-beta (TGF-β), and endothelial plasminogen activator inhibitor (PAI-1) in the pathophysiology of mental disorders such as depression has been reported before." (PMID 34516574, 2021). "Evidence is emerging that Galectin-3 may also play a role in behavioral pattern of mice and may be involved in the various forms of behavioral alterations, such as mood disorders (anxiety and depression), cognitive dysfunctions, attention deficits, and psychosis." (PMID 32455781, 2020). "Additionally, air pollution can activate inflammatory response pathways (e.g., IL1RN, galectin-3, CLEC4D, CASP8), disrupting neurotransmitter balance and exacerbating neuronal inflammation, thereby increasing the incidence of depression." (PMID 40611827, 2025). "Neither has it been explored whether low sTWEAK, high galectin-3, high HbA1c and low HDL-cholesterol were independently associated with depression." (PMID 33261587, 2020).
dilated cardiomyopathy (15 papers, 2018 to 2025). Cardiomyopathy which is characterized by dilation and contractile dysfunction of the left and right ventricles. "In dilated cardiomyopathy, circulating galectin-3 levels correlate with ECM fibrosis, suggesting its involvement in cardiac remodeling." (PMID 39063659, 2024). "The LGALS3 gene encodes the galectin-3 (35-kDa) protein, and single nucleotide polymorphisms (SNPs) and promoter-regulated expression of LGALS3 are considered potential candidates that cause CVDs, especially CAD, dilated cardiomyopathy, and HF." (PMID 34774109, 2021). "Notably, Lgals3 is down-regulated in endothelial cells under dilated cardiomyopathy pathology, which raises the possibility that the moderate up-regulation of Lgals3 in endothelial cells could benefit cardiac health." (PMID 41082647, 2025). "Moreover, there are some trials suggesting that galectin-3 may be regarded as a biomarker in the diagnosis of dilated cardiomyopathy, arrhythmogenic right ventricular cardiomyopathy, or left ventricular hypertrophy." (PMID 33801193, 2021). "All mouse models (dilated cardiomyopathy, DCM; fibrotic cardiomyopathy, ischemia-reperfusion, I/R; treatment with β-adrenergic agonist isoproterenol) showed multi-fold increases in cardiac galectin-3 expression and preserved renal function." (PMID 29844319, 2018). "Dilated cardiomyopathy lacks myocardial inflammatory infiltration, and therefore the plasma galectin-3 levels were not increased in patients with hypertrophic cardiomyopathy or dilated cardiomyopathy if there was no concomitant renal dysfunction." (PMID 37513890, 2023). "However, in a mouse model of dilated cardiomyopathy, the plasma galectin-3 levels were not increased, although the cardiac content of galectin-3 was increased 50-fold." (PMID 37513890, 2023).
Hepatitis (15 papers, 2014 to 2026). Inflammation of the liver. "Third, galectin-3 deficiency can lead to a significant reduction in the incidence of concanavalin A-induced hepatitis in mice by inhibiting inflammation." (PMID 34778306, 2021). "Galectin-3 mediates the uptake of these particles into the liver, and mice deficient in galectin-3 are protected from hepatitis and fibrosis in high fat diet models." (PMID 28661458, 2017). "Alleviated disease in Gal-3 KO mice treated with recombinant Galectin-3 confirms the protective role of Gal-3 in MCMV induced hepatitis." (PMID 30800112, 2019). "On the other hand, mesenteric injuries in Lgals3−/− mice were correlated with intense inflammatory reaction in the hepatic portal zone and hepatitis." (PMID 31601823, 2019). "We have previously shown that deletion of galectin-3 gene, Lgals3, prevents ConA-induced hepatitis and that Gal-3 regulates the capacity of dendritic cells to promote NKT cell induced liver injury." (PMID 30800112, 2019). "For example, in a mouse model of hepatitis, the galectin-3 inhibitor attenuated liver damage and proinflammatory T cell-mediated cytokine release (IFN-γ- and IL-17- and IL-4 producing CD4+ T cells)." (PMID 25387690, 2014). "In contrast, in an α-GalCer–induced hepatitis mouse model, pharmacological Galectin-3 neutralization could increase the percentage of CD4+CD25+FOXP3+ Treg cells and TGF-β–producing Treg cells among liver-infiltrating cells." (PMID 41477833, 2026). "Our results provide the first evidence that Lgals3 deletion promotes MCMV-induced liver inflammation and enhances MCMV-induced hepatitis by facilitation of TNF-α-dependent hepatocyte death." (PMID 30800112, 2019).
myocarditis (15 papers, 2017 to 2024). Myocarditis is a condition that is characterized by inflammation of the heart muscle (myocardium). "Second, EMCV can not only cause myocarditis but also encephalitis, so in a future study we will examine if encephalitis per se affects serum galectin-3 levels." (PMID 30673749, 2019). "Further studies are warranted to determine whether the serum galectin-3 might be useful and early diagnostic method for cardiac degeneration of myocarditis in humans." (PMID 30673749, 2019). "Since our data clearly indicate that serum galectin-3 might be an early diagnostic method for cardiac degeneration of acute myocarditis in our preclinical mouse model, this warrants further studies to investigate whether these findings also apply for cardiac fibrosis in humans." (PMID 30673749, 2019). "In addition, measuring serum galectin-3 levels might be an early diagnostic method for detecting cardiac degeneration in acute myocarditis." (PMID 30673749, 2019). "Macrophages and galectin 3 play critical roles in CVB3-induced murine acute myocarditis and chronic fibrosis." (PMID 33656072, 2021). "DTU I isolates of Trypanosoma cruzi induce upregulation of Galectin-3 in murine myocarditis and fibrosis." (PMID 33656072, 2021). "This is the first study to analyze the relationship between cardiac localization and serum level of galectin-3 in an animal model for myocarditis after a virus inoculation." (PMID 30673749, 2019). "The time-course analysis of the lesions clearly revealed the close relationship between the infiltration of galectin-3-positive macrophages and fibrotic lesions induced by myocarditis." (PMID 30673749, 2019). "However, there are no reports investigating time-course of the histological localization and expression of galectin-3 and the correlation with its blood concentration in myocarditis." (PMID 30673749, 2019). "To test this hypothesis, we investigated the time-course of changes of cardiac and serum galectin-3 in the EMCV-infected mouse myocarditis model." (PMID 30673749, 2019). "Disruption of the galectin 3 gene did not affect viral titres but reduced acute myocarditis and chronic fibrosis compared with C57BL/6J wild-type mice." (PMID 30673749, 2019). "Abrogation of galectin-3 expression or its pharmacological inhibition does not affect viral titers but reduce acute myocarditis and chronic fibrosis, suggesting a critical role of galectin 3-producing macrophages in the induction of fibrosis subsequent to CVB3 infection." (PMID 29375564, 2017).
parasitemia (15 papers, 2009 to 2025). "Among the galectins identified so far, galectin-3 (Gal-3) has been implicated in various parasitic infections, such as malaria, Leishmania, Trypanosoma cruzi, Toxoplasma gondii, and Schistosoma mansoni." (PMID 38067100, 2023). "LGALS3 is known to be regulated during parasitic infections in various host-parasite systems, such as the mouse-Toxoplasma gondii system." (PMID 40811742, 2025). "In models of bacterial and parasitic infection, we and others have reported that galectin-3 plays a role in neutrophil recruitment to the site of infection, although the mechanisms underlying this observation are poorly understood." (PMID 32750085, 2020). "Consistently, recent reports suggest that macrophages that accumulate in the CNS during parasite infection abundantly express Galectin-3 and activated microglia phagocytose cells via Galectin-3." (PMID 31156388, 2019). "Thus, galectin-3 controls not only parasite infection and immune responses but also cardiac and digestive pathology." (PMID 35046919, 2021). "Interestingly, in mice that developed ECM, parasitemia was moderately higher in galectin-3-KO mice compared to WT mice (p<0.0137, two-way ANOVA)." (PMID 19710907, 2009). "Indeed, this hypothesis has since been supported by numerous studies demonstrating increased antibody-secreting cell numbers and antibody titers at steady state and in response to parasite infection in LGALS3–/– mice." (PMID 30564237, 2018). "Noteworthy, the lack of galectin-3 led to a drop in systemic parasitemia and increased mouse survival." (PMID 35046919, 2021). "In addition, galectin-3 was also found to be increased in the cytoplasm of the CD4+/CD8+ thymocytes and fostered the migration of this cell subset to peripheral lymphoid organs secondary to parasite infection." (PMID 35046919, 2021).
type 1 diabetes (15 papers, 2015 to 2025). "We have previously reported plasma levels of sCD163 to be linked to galectin-3 (Gal-3) and diabetic retinopathy in adults with type 1 diabetes." (PMID 36404844, 2022). "Galectin-3 deficient mice have been shown to display increased glomerular accumulation of AGEs in a model of type I diabetes and increased ox-LDL and lipoprotein products when fed an atherogenic diet." (PMID 26047815, 2015). "Intriguingly, a previous study found that genetic knock-out of Galectin-3 improved microvascular leakage and TJ integrity in streptozotocin-induced type I diabetic mice." (PMID 36076283, 2022). "For example, some of the most significantly altered MAM proteins in our Type 1 diabetes model included LGALS3, GPX4, PDGFR, AQP4, and alphaA- and alphaB-crystallin (CRYAA and CRYAB)." (PMID 36139394, 2022). "We have shown previously that Galectin-3 deletion attenuates type 1 diabetes due to its lack in immune effectors cells." (PMID 32455781, 2020). "The galectin-3 knockout has been used to study the role of galectin-3 in murine models of type I diabetes induced by streptozotocin, where both pro-diabetogenic and protective roles have been reported." (PMID 26047815, 2015). "In contrast, galectin-3 appeared to be crucial for immune mediated β-cell damage, as galectin-3 knockout mice were resistant to multiple low doses of streptozotocin, a classical model of type 1 diabetes." (PMID 26770660, 2016).